ZPLD1 (zona pellucida like domain containing 1)
Description:
Glycoprotein which is a component of the gelatinous extracellular matrix in the cupulae of the vestibular organ.
Tractability: Antibody: UniProt places it where antibodies can reach, with medium confidence; UniProt predicts a signal peptide or a membrane-spanning region; its Gene Ontology location is reachable by antibodies, with medium confidence.
Gene: Protein-coding gene on chromosome 3 (102,099,244 to 102,479,841, forward strand). Ensembl gene ENSG00000170044.
Subcellular location: Cytoplasmic vesicle membrane (Zona pellucida-like domain-containing protein 1); Secreted, extracellular space, extracellular matrix (Zona pellucida-like domain-containing protein 1, secreted form)
Subcellular location (Human Protein Atlas): Nucleoplasm
Gene Ontology:
Cellular component: cell surface; cytoplasmic vesicle membrane
Genetic constraint (gnomAD): Loss-of-function variants: 28 observed, 37.01 expected, observed/expected ratio (o/e) 0.76, 90% interval 0.56 to 1.04. The upper end of that interval is the gene's LOEUF score, 1.04, which puts it in group 4 of 6, group 1 being the genes least tolerant of losing a copy. Missense variants: 448 observed, 463.28 expected, observed/expected ratio (o/e) 0.97, 90% interval 0.89 to 1.05. Synonymous variants: 157 observed, 172.92 expected, observed/expected ratio (o/e) 0.91, 90% interval 0.8 to 1.04.
Homologues: Orthologues: chimpanzee ZPLD1 (99% identical), macaque ZPLD1 (99% identical), dog ZPLD1 (96% identical), rabbit ZPLD1 (95% identical), pig ZPLD1 (95% identical), guinea pig ZPLD1 (94% identical), rat Zpld1 (93% identical), mouse Zpld1 (92% identical), tropical clawed frog zpld1 (82% identical), zebrafish zpld1a (71% identical), zebrafish zpld1b (68% identical). Paralogues in human: TECTB (23% identical), UMOD (21% identical), GP2 (20% identical), UMODL1 (18% identical), OIT3 (17% identical).
Diseases named in the same sentence as ZPLD1 in open-access papers:
ZPLD1 is named in the same sentence as 5 diseases in open-access papers, as found by Europe PMC text mining. Sharing a sentence is not in itself a finding about the gene and the disease. The quoted sentences say what the papers report.
cerebral cavernous malformation (5 papers, 2013 to 2022). A disorder characterized by malformations in the structure of the capillaries in the brain. "In humans, a mutation in ZPLD1 was found in a patient with balanced translocation and cerebral cavernous malformations." (PMID 36009362, 2022). "ZPLD1 has been associated with onset of sensory disturbances in an independent GWAS and linked to cerebral cavernous malformations, which in turn have been linked to high incidence of epilepsy." (PMID 32381021, 2020). "This chromosomal region contains 1 gene, ZPLD1, which has been reported to be associated with cerebral cavernous malformations, a disease with enlarged small blood vessels (capillaries) in the brain." (PMID 27980647, 2016). "In humans, a ZPLD1 gene mutation leading to a 2.5-fold decreased expression level has been described in a patient exhibiting cerebral cavernous malformations (CCM)." (PMID 36430381, 2022). "Additionally, a high incidence of epilepsy is found in patients with cerebral cavernous malformations, suggesting the involvement of ZPLD1 in the nervous system." (PMID 23834954, 2013). "The functions of ZPLD1 remain unclear, but one report investigated the involvement of ZPLD1 in cerebral cavernous malformations." (PMID 23834954, 2013). "The ZPLD1 gene may be involved in the development of cerebral cavernous malformations at the mRNA expression level." (PMID 23834954, 2013). "Interestingly, however, the gene at the most significant IBD mapping region, ZPLD1, has been reported to be related to cerebral cavernous malformations, a disease with enlarged small blood vessels (capillaries) in the brain, in a patient with a balanced translocation." (PMID 27980647, 2016).
Obesity (1 paper, 2021). Accumulation of substantial excess body fat. "For instance, a significant positive association between log (root−to−tip ω) and log (body mass) was tested in BRAP, STX16, ZGRF1 and ZPLD1, and all four genes were reported to cause obesity in humans." (PMID 34107880, 2021). "In particular, three obesity-related BSAGs (ST3GAL2, ZGRF1 and ZPLD1) were determined to have undergone rapid evolution in extremely large carnivores, although this was not significant in any of the three after FDR correction." (PMID 34107880, 2021).
ZPLD1 also shares sentences with these, for which no sentence is quoted: epilepsy (2 papers); cancer (1); inflammatory bowel disease (1).